RSU1 (Ras suppressor protein 1)
Description:
Potentially plays a role in the Ras signal transduction pathway. Capable of suppressing v-Ras transformation in vitro.
Synonyms: RSP-1; FLJ31034
Tractability: PROTAC: ubiquitination databases record sites on it; its protein half-life has been measured.
Gene: Protein-coding gene on chromosome 10 (16,590,611 to 16,817,463, reverse strand). Ensembl gene ENSG00000148484.
Subcellular location (Human Protein Atlas): Vesicles
Pathways (Reactome):
Cell-Cell communication: Regulation of cytoskeletal remodeling and cell spreading by IPP complex components
Gene Ontology:
Molecular function: protein binding
Biological process: cell-matrix adhesion; Ras protein signal transduction; signal transduction
Cellular component: extracellular exosome; focal adhesion; cytosol
Genetic constraint (gnomAD): Loss-of-function variants: 14 observed, 21.11 expected, observed/expected ratio (o/e) 0.66, 90% interval 0.44 to 1.04. The upper end of that interval is the gene's LOEUF score, 1.04, which puts it in group 4 of 6, group 1 being the genes least tolerant of losing a copy. Missense variants: 292 observed, 317.68 expected, observed/expected ratio (o/e) 0.92, 90% interval 0.83 to 1.01. Synonymous variants: 152 observed, 132.17 expected, observed/expected ratio (o/e) 1.15, 90% interval 1.01 to 1.32.
Homologues: Orthologues: chimpanzee RSU1 (99% identical), macaque RSU1 (99% identical), dog RSU1 (98% identical), guinea pig RSU1 (98% identical), rabbit RSU1 (97% identical), mouse Rsu1 (97% identical), rat Rsu1 (97% identical), tropical clawed frog rsu1 (94% identical), zebrafish rsu1 (91% identical), pig RSU1 (90% identical), Drosophila melanogaster ics (58% identical), Caenorhabditis elegans rsu-1 (55% identical).
Diseases named in the same sentence as RSU1 in open-access papers:
RSU1 is named in the same sentence as 34 diseases in open-access papers, as found by Europe PMC text mining. Sharing a sentence is not in itself a finding about the gene and the disease. The quoted sentences say what the papers report.
breast carcinoma (13 papers, 2013 to 2025). "In conclusion, our data propose a novel mechanism for the regulation of the PTEN/PI3K/AKT signaling pathway in mammary epithelial and breast cancer cells by miRs targeting RSU1 and PINCH1." (PMID 32751711, 2020). "RSU1 expression is higher in some of the basal type breast cancer cell lines; PINCH1 RNA is also increased in basal cell lines but there is less variability detected for ILK and parvin." (PMID 32751711, 2020). "RSU1 expression was blocked by miR-182 in lung metastasis of mouse fibrosarcomas, as well as in a breast cancer cell line, and miR-629 targeted RSU1 in cervical cancer thereby decreasing the sensitivity to a therapeutic agent." (PMID 32751711, 2020). "Little is known regarding the role of RSU1 in hepatocellular carcinoma, with the thus far available data being in agreement with what has been shown in breast cancer." (PMID 32517326, 2020). "In the case of breast cancer cells, which express both RSU1 isoforms, the expression pattern of this isoforms should be determined for appropriate therapeutic targeting." (PMID 32517326, 2020). "Our previous work has identified the role of RSU1 in mammary epithelial and breast cancer cell lines." (PMID 32751711, 2020). "In aggressive liver and breast cancer cells, RSU1 is upregulated, and the blocking of its expression efficiently inhibits cell migration and invasion." (PMID 32517326, 2020). "In our current study, we identify the miRs targeting RSU1 and determine the expression pattern of the miRs across a collection of breast cancer cell lines." (PMID 32751711, 2020). "RSU-1 was also found upregulated in metastatic breast cancer (BC) samples and was recently demonstrated to have metastasis-promoting properties." (PMID 30621163, 2019). "RSU1 is reported to be involved in the Ras signal effects in breast cancer by inhibiting anchorage-independent cancer cell proliferation." (PMID 30161160, 2018). "Silencing of RSU1 leads to increased cell proliferation and inhibits apoptosis in breast cancer cells." (PMID 27487126, 2017). "Furthermore, overexpression of RSU1 significantly reduced human breast cancer and glioblastoma cell growth and tumorigenic potential." (PMID 33853759, 2021). "Lastly, GDF15 seems to be an important mediator of RSU1 functions both in breast cancer and in glioblastoma, but the molecular mechanism of its action, its interaction with RSU1 and possible modulators of that interaction are still unknown." (PMID 32517326, 2020). "In a recent in vitro study performed in breast cancer cells, we showed that RSU-1 silencing downregulates several actin-modulating genes, namely PARVA, RhoA, Rho associated kinase-1 (ROCK) and Fascin-1 and leads to inhibition of breast cancer cell migration and invasion." (PMID 31412547, 2019). "Similarly expression of Rsu-1 driven by an expression vector in breast cancer cell line suppressed its growth and migration." (PMID 24058607, 2013). "In conclusion, studies in breast cancer cells clearly show that both RSU1 isoforms promote breast cancer cell migration and invasion in vitro but there is also a mechanism in place by which the truncated RSU1-X1 isoform acts as a back-up for performing the functions of RSU1 when the latter is lost." (PMID 32517326, 2020). "This suggests that RSU1 could be a therapeutic anti-metastatic target in liver and breast cancer." (PMID 32517326, 2020). "To elucidate the intricate roles of ADK fusion genes in HR+/HER2‒ breast cancer, we identified several distinct fusion events involving ADK with 6 different partner genes: PCDH15, SEC24C, KAT6B, RSU1, NARS2, and LRMDA." (PMID 41213951, 2025). "We have also tested the role of RSU1 in cell–ECM adhesion–induced regulation of MEK and ERK signaling in other cell types (e.g., human MDA-MB-231 breast cancer cells), in which RSU1 was depleted using the same CRISPR/Cas9 strategy." (PMID 33853759, 2021).
breast carcinoma (continued). "miR-221-3p, known to target PTEN and cell cycle regulators, also targets RSU1 and PINCH1 in luminal breast cancer cell lines." (PMID 32751711, 2020). "This study was designed to identify miRs targeting RSU1, or members of the IPP complex, and their activity in normal breast and luminal breast cancer cell lines." (PMID 32751711, 2020). "miR transfection validated the effects of miRs on RSU1, PINCH1 and downstream targets in breast cancer cell lines." (PMID 32751711, 2020). "Ras Suppressor-1 (RSU-1), a cell-ECM adhesion protein that interacts with PINCH-1, thus being connected to Integrin Linked Kinase (ILK), alpha-parvin (PARVA), and actin cytoskeleton, is up-regulated in metastatic breast cancer (BC) samples." (PMID 31296919, 2019). "This may constitute a novel mechanism for the regulation of the PTEN/PI3K/AKT signaling pathway by miR-182-5p and -409-3p, via the targeting of RSU1 and the IPP cell adhesion complex in mammary epithelial and breast cancer cells." (PMID 32751711, 2020).
glioma (6 papers, 2019 to 2024). A benign or malignant brain and spinal cord tumor that arises from glial cells (astrocytes, oligodendrocytes, ependymal cells). "For example, loss or reduced expression or mutations of RSU1 was often found in human cancers (e.g., hepatocellular carcinoma and gliomas)." (PMID 33853759, 2021). "RSU-1 is significantly upregulated in more aggressive glioma cell types, and silencing RSU-1 can reduce STAT6 and MMP13 to inhibit invasion." (PMID 39458959, 2024). "Particularly, among the proteins over-expressed in GBM-sEVs, we noted the glioma-associated extracellular matrix antigen Tenascin C (TNC), the stemness-associated CD109 antigen, the tumor-associated CD44 antigen, the Ras suppressor protein 1 (RSU1)." (PMID 36009432, 2022). "In conclusion, the present study provides the first evidence that RSU-1 has distinct roles in glioma cell invasion depending on the cells’ aggressiveness." (PMID 31123330, 2019). "Future studies are thus needed in order to better clarify the exact mechanism in which RSU-1 and GDF15 take part in gliomas and evaluate the diagnostic potential of their expression levels." (PMID 31412547, 2019). "This, combined with the fact that GDF15 is involved in actin cytoskeleton organization, prompted us to investigate the interplay between this protein and RSU-1 with regard to glioma cell aggressiveness in vitro." (PMID 31412547, 2019). "In accordance with cell motility results, invasion capacity was also found to be decreased upon RSU-1 silencing in the most aggressive glioma cells, whereas it was increased in the least aggressive cells." (PMID 31123330, 2019). "Further investigation is, of course, warranted in order to decipher the exact mechanism of action of RSU-1 in gliomas." (PMID 31123330, 2019). "The least aggressive glioma cells (H4 and SW1088) exhibited increased motility following RSU-1 silencing in contrast to the most aggressive glioma cells (A172 and U87-MG), which exhibited decreased motility after RSU-1 silencing." (PMID 31123330, 2019). "Interestingly, we found that Ras Suppressor-1 (RSU-1), a cell-matrix adhesion protein involved in cancer cell invasion, was significantly upregulated in more aggressive glioma cells compared to less aggressive." (PMID 31123330, 2019). "Importantly, RSU-1 silencing had opposing effects on glioma cell invasion depending on their aggressiveness, inhibiting migration and invasion of aggressive cells and promoting those of less aggressive cells." (PMID 31123330, 2019). "In an attempt to elucidate the interplay between GDF15 and RSU-1 in glioma cell invasion and the molecular pathway involved, we first assessed the invasion capacity of H4, SW1088 and A172 cells using a 3-dimensional (3D) spheroid formation assay in collagen following RSU-1 silencing." (PMID 31412547, 2019). "Also, we found that PINCH1, RhoA and MMP13 play a crucial role being regulated by the RSU-1/GDF15 interplay leading to affection of the final invasive phenotype of glioma cells." (PMID 31412547, 2019). "Interestingly, we showed for the first time that RSU-1 silencing has an opposite effect on glioma cell line invasion depending on whether the cell line is aggressive or not." (PMID 31123330, 2019). "To investigate the interplay and possible connection between RSU-1 and GDF15 in glioma cells, we used three different brain cell lines, namely H4, SW1088 and A172, which have different tumoral origin, properties and proteins expression level." (PMID 31412547, 2019). "As this connection, between RSU-1 and GDF15 is not yet well-defined, in the present study, we investigated the interplay between RSU-1 and GDF15 in glioma cell lines and the effect of their expression on glioma cell migration and invasion." (PMID 31412547, 2019). "In the present study, we focused on the interplay between RSU-1 and GDF15 and their role in regulating glioma cell invasion using three different glioma cell lines (H4, SW1088 and A172)." (PMID 31412547, 2019).
glioma (continued). "Regarding brain cancer, the first report on the involvement of RSU1 in glioblastoma was made as early as in 1995, showing that the RSU1 gene is frequently deleted in high-grade gliomas, but no other evidence is available in human samples thus far." (PMID 32517326, 2020). "Apart from the original RSU1 protein, another 29 kDa isoform (namely, RSU1-X1, with NCBI Reference sequence: XM_005252552.4) produced by alternative splicing has been reported to be present in more aggressive gliomas and breast cancer cells." (PMID 32517326, 2020). "Finally, to better understand the molecular mechanism governing RSU-1 and GDF-15 in glioma cells, we proceeded to silence RSU-1 for 24 h and then treated the cells with hrGDF-15 for another 24 h." (PMID 31412547, 2019). "Intrigued by this finding, we wondered whether RSU-1 and GDF-15 are collaborating in regulating glioma cell invasion through a common molecular pathway, as both genes are indirectly associated with actin cytoskeleton reorganization and aggressive cancer cell behavior." (PMID 31412547, 2019). "Surprisingly, RSU-1 silencing did not have the same effect in all four glioma cell lines tested." (PMID 31123330, 2019).
hepatocellular carcinoma (6 papers, 2013 to 2021). A malignant tumor that arises from hepatocytes. "Further, overexpression of Rsu-1 in hepatoma cell lines leads to its association with PINCH1 followed by reduced cell proliferation and migration." (PMID 24058607, 2013). "The tumor suppressor role of RSU1 is further corroborated by the fact that RSU1 is frequently deleted in hepatocellular carcinomas." (PMID 32517326, 2020). "Our findings further corroborate recent work showing that RSU-1 depletion from hepatocellular carcinoma cells inhibits cell invasion, and additionally demonstrate that this holds true for BC cells as well." (PMID 28423706, 2017). "In view of recognized difficulties with transfection of normal hepatocytes, we overexpressed Rsu-1 in hepatoma cell lines Hep3B and Huh-7 and found that it led to decreased proliferation and migration respectively." (PMID 24058607, 2013). "Furthermore, a somatic copy number variation (CNV) analysis in hepatocellular carcinoma samples showed that the Rsu-1 gene exhibited a high frequency of CNVs with 7 deletions and 3 amplifications indicating that Rsu-1 is frequently deleted in human liver cancer." (PMID 28423706, 2017). "In addition, we screened several hepatoma cell lines for the levels of Rsu-1." (PMID 24058607, 2013). "More specifically, RSU1 expression was found to be dramatically elevated in more aggressive HepG2 hepatocellular carcinoma cells compared to the non-metastatic Alexander cells and its elimination promoted cell proliferation." (PMID 32517326, 2020).
liver cancer (4 papers, 2013 to 2020). An epithelial or non-epithelial malignant neoplasm that arises from the liver. "We have recently found that PINCH binding partner protein Rsu-1 is frequently deleted in human liver cancers." (PMID 24058607, 2013). "RSU-1 localizes to cell-ECM adhesion sites through its interaction with PINCH-1 and has been shown to promote the metastatic behavior in breast and liver cancer cells in vitro." (PMID 31412547, 2019). "Ras suppressor 1 (Rsu-1) protein, the binding partner of PINCH is frequently deleted in human liver cancers." (PMID 24058607, 2013). "Rsu-1, a partner for PINCH and a protein often deleted in human liver cancer and markedly decreased in the PINCH DKO mice may play an important role in this process." (PMID 24058607, 2013). "Decreased levels of Rsu-1, a partner for PINCH and a protein often deleted in human liver cancer, may play an important role in the development of the observed phenotype." (PMID 24058607, 2013). "From a totally separate study in our lab utilizing liver cancers, we also found that 10% of the HCC patients had deletions in Rsu-1 gene further strengthening our hypothesis that Rsu-1 might be a major negative growth regulator for hepatocytes." (PMID 24058607, 2013).
cervical cancer (3 papers, 2020 to 2021). A primary or metastatic malignant neoplasm involving the cervix. "In cervical cancer, it was noticed that the knockdown of either miR-210 or miR-629 sensitizes cells to ACA by upregulating SMAD family member 4 (SMAD4) or Ras suppressor protein 1 (RSU1), respectively." (PMID 33066509, 2020).
prostate carcinoma (3 papers, 2019 to 2020). A carcinoma that arises from epithelial cells of the prostate gland. "The miR-409-3p/5p-dependent depletion of RSU1 occurs following the epithelial uptake of stromal-produced exosomes in early prostate tumors; the use of miR-409 antagomiRs restored the RSU1 protein and decreased bone metastasis in a mouse model of aggressive prostate cancer." (PMID 32751711, 2020).
brain cancer (2 papers, 2019 to 2020). A primary or metastatic malignant neoplasm affecting the brain. "As RSU1 has been previously linked to basic functions of the CNS, it is not surprising that it is also involved in the pathogenesis of glioblastoma, the most aggressive type of brain cancer." (PMID 32517326, 2020). "In brain cancer cells, there is only one RSU1 isoform expressed, but its mode of action depends on its expression level." (PMID 32517326, 2020). "In this review, we summarize recent studies using breast, liver and brain cancer cell lines and highlight the role of RSU1 in regulating cancer cell invasion." (PMID 32517326, 2020). "In aggressive brain cancer cells, which express RSU1 at high levels, RSU1 promotes cell invasion and migration, and thus, inhibiting it would be therapeutically beneficial." (PMID 32517326, 2020). "RSU-1, which binds to PINCH1 at FA sites has been previously found to be upregulated in more invasive breast and brain cancer cells." (PMID 31412547, 2019).
colon cancer (2 papers, 2017 to 2019). "Interestingly, an alternatively-spliced variant of rsu-1 was identified in 30% of high grade gliomas and 2/3 of oligodendrogliomas but not in other brain, bladder, colon tumors of normal tissue while rare RSU-1 deletion were also identified in three cancer types from the Cancer Genome Atlas." (PMID 28423706, 2017).
glioblastoma (2 papers, 2013 to 2020). The most malignant astrocytic tumor (WHO grade IV). "Transient overexpression of RSU1 in U251 glioblastoma cells that express low levels of RSU1 reduced their growth rate in vivo and reduced aggressive cell behavior, again indicating that RSU1 likely acts as a tumor-suppressor gene." (PMID 32517326, 2020). "Studies have shown that Rsu-1 has suppressive effects on growth of cancer cells namely glioblastoma and mammary cells." (PMID 24058607, 2013). "Thus, RSU1 apparently has distinct roles with regard to glioblastoma cell invasion depending on the cells’ aggressiveness as well as based on its expression level in the specific cells." (PMID 32517326, 2020).
lung adenocarcinoma (2 papers, 2022 to 2023). A carcinoma that arises from the lung and is characterized by the presence of malignant glandular epithelial cells. "A recent study reported that ILK promotes lung adenocarcinoma progression and metastasis through the regulation of KRAS, the IPP complex and RSU1, with other studies also linking ILK to cancer metastasis." (PMID 37568580, 2023). "In lung adenocarcinoma, as reported, ILK can regulate KRAS, IPP complex and Ras suppressor-1 (RSU1) to promote cancer cell multiplication, migration and epithelial-mesenchymal transition (EMT), and its high expression is pertinent to poor prognosis." (PMID 35029589, 2022).
metastatic tumors (2 papers, 2019 to 2024). "CHMP1A, B2M, and RSU1 loss alterations were significantly enriched in RB1-loss primary tumors at a frequency of 7%–18% above RB1-WT primary tumors and were significantly enriched in RB1-loss metastatic tumors at a frequency of 16%–23% above RB1-loss primary tumors." (PMID 38751776, 2024).
alcohol dependence (1 paper, 2017). Physical and psychological dependence on alcohol. "Human genome-wide association studies have found correlations between Rsu1 SNP and ventral striatum activity, and a mutation in Rsu1 is associated with alcohol dependence." (PMID 29391952, 2017).
breast tumor (1 paper, 2020). "We show that RSU1 is a direct target of miR regulation in both normal and luminal breast tumor cell lines." (PMID 32751711, 2020).
colorectal cancer (1 paper, 2011). A primary or metastatic malignant neoplasm that affects the colon or rectum.